RN7SL63P (RNA, 7SL, cytoplasmic 63, pseudogene)
Gene: Miscellaneous RNA gene on chromosome 10 (30,555,601 to 30,555,904, reverse strand). Ensembl gene ENSG00000239744.
Homologues: Orthologues: chimpanzee Metazoa_SRP (98% identical), macaque Metazoa_SRP (90% identical). Paralogues in human: RN7SL1 (82% identical), RN7SL2 (82% identical), RN7SL296P (81% identical), RN7SL3 (81% identical), RN7SL664P (79% identical), RN7SL479P (79% identical), RN7SL220P (79% identical), RN7SL498P (78% identical), RN7SL566P (78% identical), RN7SL709P (78% identical), RN7SL88P (78% identical), RN7SL14P (78% identical), and 696 more.